LINC01980 (long independently transcribed non-coding RNA 1980)
Gene: Long non-coding RNA gene on chromosome 3 (27,796,694 to 27,931,579, forward strand). Ensembl gene ENSG00000225548.
Diseases named in the same sentence as LINC01980 in open-access papers:
LINC01980 is named in the same sentence as 7 diseases in open-access papers, as found by Europe PMC text mining. Sharing a sentence is not in itself a finding about the gene and the disease. The quoted sentences say what the papers report.
esophageal squamous cell carcinoma (4 papers, 2021 to 2023). Esophageal squamous cell carcinoma (ESCC) is a type of esophageal carcinoma (EC) that can affect any part of the esophagus, but is usually located in the upper or middle third. "It was previously reported that LINC01980 is overexpressed in esophageal squamous-cell carcinoma and acts as an endogenous competing RNA to regulate the downstream pathway and promote the development of esophageal cancer." (PMID 35877251, 2022). "Up-regulated expression of LINC01980 in esophageal squamous cell carcinoma confers poor prognosis and as well promotes epithelial-mesenchymal transition (EMT) via the miR-190a-5p and MYO5A pathways." (PMID 33767582, 2021). "For example, linc01980 has been reported to promote esophageal squamous cell carcinoma progression." (PMID 35083327, 2022).
colorectal cancer (1 paper, 2025). A primary or metastatic malignant neoplasm that affects the colon or rectum. "LINC01980, as a lncRNA newly discovered in recent years, is aberrantly expressed in multiple neoplastic conditions, such as esophageal, gastrointestinal, and colorectal cancers, and is involved in tumor proliferation and metastasis." (PMID 41390751, 2025).
hepatocellular carcinoma (1 paper, 2021). A malignant tumor that arises from hepatocytes. "Upregulated expression and tumorigenic potential of LINC01980 has also been observed in hepatocellular carcinoma cell lines Huh7 and Hep3B." (PMID 34898376, 2021).
tumor (3 papers, 2021 to 2025). "Rescue experiments confirmed that the depletion of miR-204-3p reverses the tumor-suppressive effects caused by LINC01980 knockdown, indicating that the oncogenic function of LINC01980 is dependent on its negative regulation of miR-204-3p." (PMID 41390751, 2025). "A body of evidence indicates that miR-204-3p functions as a tumor suppressor, suggesting that LINC01980 is likely to influence LUSC development by regulating miR-204-3p expression." (PMID 41390751, 2025). "The experimental data from this study showed significant downregulation of miR-204-3p expression in LUSC tumor tissues and cellular models, and it targets and binds to LINC01980." (PMID 41390751, 2025). "Moreover, the expression level of LINC01980 in the LUSC samples showed a strong correlation with tumor stage." (PMID 41390751, 2025). "The specific role of LINC01980 is rarely reported in tumor biology." (PMID 36445051, 2023). "AC093895.1, CASC9, HOXC-AS2, and LINC01980 may be involved in tumor progression, and the molecular mechanism remains to be further verified." (PMID 36445051, 2023). "Despite this finding, the expression patterns of LINC01980 in LUSC patients, as well as the functional consequences of its interaction with miR-204-3p on tumor progression, remain poorly understood." (PMID 41390751, 2025). "Mechanistically, forced (over)expression of LINC01980 in ESCC cell lines has been shown to promote Myosin-Va (MYO5A) expression by inhibiting miR-190a-5p, resulting in enhanced tumor cell proliferation and EMT." (PMID 34898376, 2021). "Expression correlation analysis noted a significant negative correlation between miR-204-3p and LINC01980 in tumor tissues (r=−0.531, P < 0.0001)." (PMID 41390751, 2025). "WGCNA and Kaplan-Meier survival analysis revealed that 5 DELs (MIR4435-2 HG, CASC9, LINC01980, STARD4-AS1 and MIR99AHG) were significantly correlated with OS of HNSCC patients, whereas DEL PART1 was most significantly correlated with the HNSCC tumor." (PMID 34898376, 2021).
cancer (1 paper, 2025). A tumor composed of atypical neoplastic, often pleomorphic cells that invade other tissues. "Although LINC01980 has been implicated in the development of several cancers, its specific mechanisms in LUSC remain unclear." (PMID 41390751, 2025).
LINC01980 also shares sentences with these, for which no sentence is quoted: esophageal cancer (1 paper); gastric cancer (1).